G6PD (glucose-6-phosphate dehydrogenase)
Diseases named in the same sentence as G6PD in open-access papers (continued):
Sharing a sentence is not in itself a finding about the gene and the disease.
infection (113 papers, 2008 to 2026). The state of being infected such as from the introduction of a foreign agent such as serum, vaccine, antigenic substance or organism. "Unexpectedly, G6PD-deficient mice showed decreased lung bacterial burden (p=0.05) compared to controls 24-h post-infection." (PMID 38559268, 2024). "Several studies identified a slew of life-threatening infections in G6PD-deficient patients, with bacteremia, respiratory, cerebrospinal, and urinary tract infections being the most common." (PMID 36978361, 2023). "As long as the in vitro studies translate to human physiology, these results further support the positive feedback loop between ROS concentration and viral load, resulting in a higher risk of severe infection in G6PD-deficient patients." (PMID 36905446, 2023). "Elevated levels of oxidative stress as a result of G6PD deficiency cultivate a favorable environment for viral replication, consequently deteriorating the course of infection." (PMID 36905446, 2023). "One study specifically identified the infection as a risk factor of cardiovascular disease development in elderly G6PD-deficient patients." (PMID 36905446, 2023). "G6PD-deficient individuals are susceptible to the development of favism, neonatal jaundice and infection/drug-induced hemolysis primarily due to oxidative stress." (PMID 36271440, 2022). "A plethora of bacterial and fungal infections was identified in several studies that described the infections in G6PD-deficient patients, among which pneumonia, gastrointestinal, osteomyelitis, cerebrospinal, and septicemia were more common." (PMID 35884188, 2022). "Another study showed that there is an increase in the expression of the TNF-α in human G6PD-deficient alveolar epithelial cells with carcinoma after the infection with HCoV-229E." (PMID 35805067, 2022). "Another study reported that α-lipoic acid attenuates the vulnerability of G6PD-deficient cells and proposed it as a treatment option for infection SARS-CoV-2 in patients with this deficiency." (PMID 35805067, 2022). "Over five years, all adult G6PD-deficient patients admitted to the hospital with microbiological proof of infection at admission or during hospitalization were studied." (PMID 35884188, 2022). "Pathogen infections are more likely to occur in G6PD-deficient subjects because they have a decreased ability to activate the innate immune response." (PMID 36091812, 2022). "After obtaining ethical approval, a registry of recorded cases was consulted retrospectively to include G6PD-deficient adult patients admitted to Suhar hospital over 5 years with microbiologically confirmed infections." (PMID 35884188, 2022). "Glucose-6-phosphate dehydrogenase (G6PD) has also been suggested to play a role in COVID-19 infection and severity and has also been associated with infection of cells with human coronaviruses." (PMID 33679730, 2021). "Radical cure involves treating the blood stage of infection and combining it with an antimalarial active against hypnozoites, where the latter presents a risk of haemolysis in G6PD deficient individuals." (PMID 34551751, 2021). "To understand the interaction between G6pd deficiency and P.berghei infection, we conducted dual RNA-seq for G6pd-deficient mice and P.berghei pathogen on day 7 post-infection." (PMID 34456927, 2021). "Using dual RNA-seq in liver tissue, we can obtain and analyze the transcriptome information of kinetic gene expression in both G6pd-deficient mice and P.berghei during infection." (PMID 34456927, 2021). "Reduced G6PD activity due to a mutation predisposes G6PD-deficient individuals to red cell disorders, including favism, neonatal jaundice and drug- or infection-induced hemolysis." (PMID 33217954, 2020). "They demonstrated that G6PD (glucose-6-phosphate dehydrogenase) deficient cultured cells are more susceptible to coronavirus-induced infection compared to normal cells." (PMID 33294461, 2020).
infection (continued). "For example, in an in vitro study, after infection with human coronavirus (HCoV) 229E, the production of viral particles in G6PD-deficient or G6PD-knockdown cells was higher than in healthy cells, and this was correlated with increased oxidant production." (PMID 32161622, 2020). "The important contribution of relapses to the burden of P. vivax is further highlighted by the observation that G6PD deficient children had a higher prevalence of P. vivax infection and increased risk of acquiring new infection." (PMID 30922304, 2019). "Most G-6-PD deficient individuals should avoid the oxidative stress triggered by agents such as antimalarial drugs (primaquine, dapsone or tafenoquine), infection, or the ingestion of fava beans." (PMID 31860695, 2019). "G6PD-deficient monocytes are more sensitive to infection by the dengue virus and have redox imbalance compared to matched control monocytes." (PMID 31500396, 2019). "G6PD-deficient individuals tend to suffer from red cell disorders, including jaundice and drug- or infection-induced hemolytic anemia." (PMID 31500396, 2019). "Pretreatment with antioxidant N-acetylcysteine (NAC) confers resistance to infection of G6PD-deficient cells." (PMID 31500396, 2019). "The predominance of infections with P. vivax, combined with moderate levels of serious G6PD deficiencies highlight the need for careful rollout of primaquine towards elimination goals." (PMID 29859089, 2018). "Risk factors for infection were examined using logistic regression; and a randomized subset of males was tested for glucose-6-phosphate dehydrogenase (G6PD) deficiencies using a combined PCR and sequencing approach." (PMID 29859089, 2018). "Haemolysis in G6PD-deficient individuals was caused not only by primaquine but also by other medicines and infections." (PMID 29082022, 2017). "Of the 13 patients with P. vivax, P. ovale, mixed infection, or undetermined species infection, nine (69%) received terminal prophylaxis with primaquine, after exclusion of deficiency of glucose-6-phosphate dehydrogenase (G6PD)." (PMID 28743266, 2017). "In particular, phenotypic G6PD enzyme deficiency was associated with decreased risk of symptomatic infection, as seen for human-only Plasmodium species, and is probably related to long-term selection pressure from these human-only species." (PMID 28758162, 2017). "Knockdown of TNF-α expression can enhance HCoV-229E replication, whereas TNF-α pretreatment can decrease the susceptibility of infection in G6PD-knockdown A549 cells." (PMID 26694452, 2015). "The lower levels of endogenous NO production induced after the infection of G6PD-deficient monocytes correlate with the accelerated replication of DENV2 in these cells." (PMID 24625456, 2014). "Monocytes from G6PD-deficient individuals exhibited significantly higher infection rates compared to normal controls." (PMID 24625456, 2014). "The peak O2.− levels were noticed at an earlier time point (24 hours post infection) in G6PD-deficient monocyte cultures compared to normal control monocyte cultures (48 hours post infection)." (PMID 24625456, 2014). "The peak oxidative stress accumulation was noticed at an earlier time point (72 hours post infection) in G6PD-deficient monocyte cultures compared to normal control monocyte cultures (96 hours post infection)." (PMID 24625456, 2014). "In G6PD-deficient monocyte cultures, increased O2.− levels were observed until 24 hours post infection, when peak values of 23.3% were reached." (PMID 24625456, 2014). "DENV2 released from 16 G6PD-deficient monocyte cultures showed mean peak titers of 37×102 PFU/ml on the 48 hours post infection." (PMID 24625456, 2014). "In G6PD-deficient monocyte cultures, increased NO produced until 48 hours post infection, when peak values were reached followed by a decrease." (PMID 24625456, 2014).
infection (continued). "The lower level of endogenous O2.− generation induced after the infection of G6PD-deficient monocytes seems to markedly enhance the course of DENV2 infection in these cells." (PMID 24625456, 2014). "NO released from 16 G6PD-deficient monocyte cultures showed mean peak levels of 603.75 μM L−1 at 48 hours post-infection." (PMID 24625456, 2014). "In G6PD-deficient monocyte cultures, oxidative stress accumulation increased until 72 hours post infection, when peak levels of 84.4% were reached." (PMID 24625456, 2014). "The peak DENV2 titers were detected at an earlier time point (48 hours post infection) in G6PD-deficient monocyte cultures compared to normal control monocyte cultures (72 hours post infection)." (PMID 24625456, 2014). "Recently, it has been shown that infection by particular viruses, such as enterovirus 71, dengue virus, and coronavirus, was enhanced in G6PD-deficient cells." (PMID 24223971, 2013). "We further propose that the capacity for ROS removal is impaired in G6PD-deficient cells following infection-induced oxidative stress." (PMID 24223971, 2013). "Deficiency of enzyme G6PD is more prevalent in Africa, Asia, Mediterranean region and Middle East, likely due to higher prevalence of infection with Plasmodium falciparum." (PMID 24575273, 2013). "The effect of vancomycin-treated VRSA infection on A549 cells and their G6PD-deficient counterparts was investigated." (PMID 24223971, 2013). "The mutation in G6PD probably leads to granulocyte dysfunction, preventing the clearing of the infection at the first line of defense and thereby increasing susceptibility to DENV." (PMID 18270558, 2008). "Experimental results indicated that the monocytes of G6PD-deficient patients exhibited a greater levels of infection with DENV-2 New Guinea C strain than did those in healthy controls [mean±SD:33.6%±3.5 (27.2%∼39.2%) vs 20.3%±6.2 (8.0%∼30.4%), P<0.01]." (PMID 18270558, 2008). "Several studies have indicated that the abnormal function of leucocytes increases susceptibility to infection, such as by hepatitis A, in G6PD-deficient patients, causing more severe initial clinical presentations." (PMID 18270558, 2008). "In addition to altering the redox equilibrium, G6PD dysregulation/deficiency leads to defective cell growth and signaling, and infection susceptibility." (PMID 39819313, 2025). "G6PD-deficient individuals also produce lower levels of pro-inflammatory cytokines, IL-6, and IL-1β in peripheral mononuclear cells, and their granulocytes display diminished bactericidal activity and increased susceptibility to infection." (PMID 37753082, 2023). "G6PD level is elevated in M1-MΦs and cells deficient in G6PD have a reduced ability to induce the innate immune response, thereby increasing host susceptibility to infection with pathogens." (PMID 36993975, 2023). "Early studies have confirmed that G6PD-deficient patients may display impeded neutrophilic function and impaired NETs, potentially affecting the immune system’s ability to clear infections." (PMID 36905446, 2023). "An early in vitro study has illustrated that a deficiency in G6PD may increase human susceptibility to infection by coronavirus 229E." (PMID 36905446, 2023). "The deficiency of G6PD leads to premature loss of cell integrity under the stress of sulfa-containing drugs, certain foods, and systemic infections, which explains why many studies suggested G6PD deficiency to be a significant predictor of hospitalization and severe infections." (PMID 36978361, 2023). "This retrospective analysis aimed to identify the variables that may contribute to the high infection-related mortality rates in G6PD-deficient patients." (PMID 36978361, 2023). "In a previous study by the same research group, we monitored the pattern of infection in an adequate number of G6PD patients, allowing us to vividly describe the causes and risk factors for nosocomial infections and infections with multi-drug resistant (MDR) bacteria." (PMID 36978361, 2023).
infection (continued). "Furthermore, in vitro infection of G6PD-deficient fibroblasts with human coronavirus 229E yielded nearly 12-fold higher viral gene expression, 3-fold higher viral protein production, and reduced cell viability, compared with results with normal fibroblasts." (PMID 35287717, 2022). "G6PD-deficient individuals have increased susceptibility to haemolysis upon exposure to oxidative agents, including primaquine and tafenoquine which are the only medications effective for the radical treatment of infection by P. vivax and P. ovale." (PMID 33879156, 2021). "The complex haemolytic toxicity problem of primaquine in G6PD deficient patients puts that drug out of the reach of approximately 14% of people living at risk of infection by P. vivax (assuming an equal risk of infection across the population, see Footnotes 1, 2)." (PMID 29357870, 2018). "Therefore, generally asymptomatic, G6PD-deficient individuals are at risk of drug-, food- or infection-induced acute haemolytic anaemia." (PMID 29065882, 2017). "Hsieh and colleagues demonstrated that the G6PD deficient epithelial cells infected with Staphylococcus aureus compared to normal infected epithelial cells have an accumulation of more oxidants and a higher apoptosis rate during infection." (PMID 27974910, 2016). "Consumption of certain foods such as fava beans, legumes; infection with bacteria or virus; and use of certain drugs such as primaquine, sulfa drugs etc. may result in lysis of RBCs in G6PD deficient individuals." (PMID 27880809, 2016). "The information collected included: diagnosis of ABE at hospital presentation; general characteristics such as place of birth, source of referral, and sex; and a selection of suspected causes of jaundice including prematurity, infection, G6PD status, ABO and Rh incompatibility." (PMID 27057339, 2015). "Enhanced infection of G6PD-deficient monocytes by DENV may be attributable to increased viral receptors on these cells or greater production of viral particles or a combination of both." (PMID 24625456, 2014). "A combination of granulocyte dysfunction and enhanced replication of DENV in monocytes of G6PD-deficient individuals may prevent the clearing of the primary infection thus predisposing infected individuals to severe form of disease." (PMID 24625456, 2014). "Moreover, the peak infection was delayed by 24 hours in monocytes from normal controls compared to monocytes from G6PD-deficient subjects." (PMID 24625456, 2014). "Upon infection of a G6PD-deficient erythrocyte, P. falciparum induces its own G6PD." (PMID 20927393, 2010). "The mechanism of increased infection with DENV-2 in monocytes from G6PD-deficient patients remains unclear." (PMID 18270558, 2008). "Infection-induced hemolysis, involving many microbial agents, may be a common cause of clinically significant hemolytic anemia in G6PD-deficient patients, but its mechanism is unclear." (PMID 18270558, 2008). "Comparing the infection capability of the two DENV-2 stains clearly reveals that more infected cells were present in 16681 than in New Guinea C-infected monocytes (P<0.05) that were collected from either G6PD-deficient patients or healthy controls." (PMID 18270558, 2008). "Additionally, worsened prognoses and more severe complications of infection may be realized in class I G6PD-deficient individuals." (PMID 36905446, 2023). "To clarify whether G6pd deficiency modulates Nrf2 and Ho-1 proteins expressions in the early stages of P.berghei infection, we examined and quantified the Nrf2 and Ho-1 proteins expressions in mice liver and spleen on day 7 post-infection." (PMID 34456927, 2021). "Females with the BB, BA & BA- G6PD genotypic variants had a higher prevalence of Plasmodium falciparum infection relative to the females with the AA, AA- A-A- variants, whilst males with the B genotype had higher infection prevalence relative to those with the A, & A- variants." (PMID 34570821, 2021).
infection (continued). "In addition, they may also be valuable to G6PD-deficiency populations in developing countries, where hemolytic crisis-triggering factors (e.g., infection, food, and drugs) are still common." (PMID 32102234, 2020). "Eradicating the infection remains at best a long-term goal, until a drug effective against the hypnozoite that is also safe for wide deployment becomes available; today we only have 8-aminoquinolines, whose use is limited by toxicity in glucose-6-phosphate dehydrogenase deficient populations." (PMID 27799636, 2016). "In addition, a case report showed that infection by Clostridium difficile may have triggered hemolysis and led to severe jaundice in a G6PD-deficient neonate, while another case report described hemolysis caused by Acinetobacter baumannii infection." (PMID 24223971, 2013). "Therefore, the greater infection of DENV in human monocytes from G6PD-deficient patients may be associated with the low activity of ROS in monocytes, which exhibit reduced activity for eliminating the invaded DENV-2 in infected cells." (PMID 18270558, 2008). "Previous reports indicate that G6PD overexpression in macrophages reduces ROS production in response to inflammation, while inhibition of G6PD activity weakens cell resistance to infection, thereby increasing cell death." (PMID 41321495, 2025). "measured G6PD activity in patients from Bangladesh, Indonesia, and Ethiopia at the time of malaria infection and 6 to 33 months after the infection." (PMID 38725027, 2024). "Glucose-6-phosphate dehydrogenase (G6PD) is an enzyme involved in the protection of red blood cells against oxidative stresses, the most common being infection." (PMID 39144870, 2024). "It is also reported that oxidative stress upon infection with influenza virus leads to the increased acetylation of a redox homeostasis mediator, Glucose-6-phosphate dehydrogenase (G6PD), and it is strictly dependent on the expression of SIRT2." (PMID 38251346, 2023). "Both studies recruited more than 36 males with P. vivax active infection allowing determination of the AMM amongst P. vivax infected G6PD normal males." (PMID 37824592, 2023). "Influenza virus A/PR/8/H1N1 (PR8) infection induced a significant decrease in G6PD protein expression by 60%." (PMID 35071051, 2021). "Fever and infection, and the treatment of those infections with oxidative drugs can perturb the phenotypic G6PD activity steady state." (PMID 33790795, 2021). "Since G6PD levels were also reduced in mock-infected treated cells (data not shown), our data suggest a direct correlation between SIRT2 and G6PD activity during infection." (PMID 35071051, 2021). "Expression of G6PD mRNA was found to decrease at 8 h after infection until 24 h (*P < 0.05), while G6PD protein levels significantly decreased beginning at 16 h p.i (*P < 0.05)." (PMID 35071051, 2021). "Post-infection upregulated 20 transcripts in B-48, including G6PD (6 DEGs), GSDH (3 DEGs), GDPGP1 (4 DEGs), GPI (1 DEG), UGDH (1 DEG), UGPUT (3 DEGs), UGGT (1 DEG) and GPT2 (1 DEG)." (PMID 34948367, 2021). "The expression of G6PD protein in Lv‐piRNA823 infected cells increased significantly 72 hours after infection (P < .01, vs uninfected control group or NC control group)." (PMID 32596991, 2020). "Western blotting data showed that 72 hours after Lv‐piRNA82 infection, the expression of G6PD protein was significantly enhanced in two groups (P < .01, vs uninfected control group or NC control group)." (PMID 32596991, 2020). "The expression of G6PD protein in cells increased significantly 72 hours after Lv‐piRNA‐823 infection (P < .01, vs‐uninfected control group or NC control group)." (PMID 32596991, 2020). "The rate limiting enzyme of the oxidative pathway, glucose-6-phosphate dehydrogenase, is expressed at or slightly above uninfected levels for the majority of infection, 6 to 36 HPI." (PMID 32255806, 2020).